GLP1R (glucagon like peptide 1 receptor)
Diseases named in the same sentence as GLP1R in open-access papers (continued):
Sharing a sentence is not in itself a finding about the gene and the disease.
liver disease (17 papers, 2018 to 2026). "Semaglutide, a glucagon-like peptide-1 receptor agonist (GLP-1 RA), improves metabolic health and reduces liver fat in people with HIV (PWH) and metabolic dysfunction-associated steatotic liver disease (MASLD)." (PMID 41256006, 2025). "We next investigated the impact of GIPR and GLP1R modulation on liver disease and liver enzyme outcomes using GWAS summary statistics from European-ancestry cohorts." (PMID 40931165, 2025). "This discovery contributes to the evolving understanding of GLP‐1RA's role in hepatic pathology and potentially in the development of GLP‐1R targeted therapy for liver diseases." (PMID 40277442, 2025). "Given the well-established role of alcohol in liver disease progression, larger and more refined ALD GWAS datasets are necessary to clarify whether GIPR and GLP1R agonism directly mitigates ALD risk." (PMID 40931165, 2025). "Thus, it is premature to consider GLP-1R agonists to specifically treat liver disease in patients with NAFLD or NASH10." (PMID 30405191, 2018). "Glucagon-like peptide-1 receptor agonists (GLP-1RAs) are revolutionizing the management of metabolic and liver diseases, demonstrating effectiveness in controlling blood sugar levels and promoting liver repair." (PMID 41939830, 2026).
Sepsis (17 papers, 2016 to 2026). Sepsis is defined as life-threatening organ dysfunction caused by a dysregulated host response to infection. "The activation of GLP-1R can promote the proliferation of B lymphocytes and T lymphocytes, especially the expression of Treg1, to inhibit systemic inflammatory response in sepsis patients." (PMID 34335269, 2021). "GLP-1R expression in the renal cortex was significantly decreased in the sepsis and CKD-with-sepsis groups compared to the control." (PMID 31795376, 2019). "GLP-1R expression in renal tubules was decreased at 3 h, increased at 24 h, and decreased at 72 h after sepsis induction." (PMID 31795376, 2019). "The sepsis-with-CKD group showed decreased GLP-1R expression in the renal cortex compared to the CKD-only group." (PMID 31795376, 2019). "This is, to our knowledge, the first study of changes in renal GLP-1R expression in sepsis." (PMID 31795376, 2019). "The CKD-with-sepsis group showed the lowest tubular GLP-1R activity." (PMID 31795376, 2019). "Although we could not demonstrate changes in renal blood flow or sodium excretion in sepsis, the increase in GLP-1R expression in early sepsis might explain the early increase in the angiotensin II level." (PMID 31795376, 2019). "GLP-1R expression in the renal cortex decreased to lower than the control at 3 days after sepsis." (PMID 31795376, 2019). "We found that renal GLP-1R activity was increased in early sepsis, possibly due to acute inflammation, which may decrease after tissue injury." (PMID 31795376, 2019). "Therefore, we investigated GLP-1R expression in renal tubules in sepsis-related AKI and in CKD." (PMID 31795376, 2019). "Induction of GLP-1R expression may protect against inflammation and sepsis-induced AKI." (PMID 31795376, 2019). "These protective effects were absent in GLP-1R deficient (Glp1r^Wnt1−/−) mice, highlighting the critical role of neuronal GLP-1R signaling in mediating the anti-inflammatory and organ-protective actions of GLP-1RAs in sepsis." (PMID 41357527, 2025). "We compared renal GLP-1R expression at 3, 6, 12, 24, and 72 h after cecal perforation, and in CKD and CKD-with-sepsis." (PMID 31795376, 2019). "The band density of GLP-1R in intestinal tissue was markedly decreased in the sepsis, CKD, and CKD-with-sepsis groups compared to the control." (PMID 31795376, 2019). "Intestinal GLP-1R activity is thought to be lower than that in the renal cortex in patients with sepsis and CKD-with-sepsis." (PMID 31795376, 2019). "IHC showed that renal GLP-1R expression was decreased in the sepsis, CKD, and CKD-with-sepsis groups." (PMID 31795376, 2019). "We compared changes in GLP-1R expression in the kidney among animals with sepsis, CKD, and CKD-with-sepsis; however, further studies of DPP-4 in sepsis are warranted." (PMID 31795376, 2019). "GLP-1R expression in renal tubules was increased in early sepsis and later decreased by kidney injury, but was decreased in the CKD and CKD-with-sepsis groups." (PMID 31795376, 2019). "glucagon-like peptide-1 receptor agonists (GLP-1RAs) not only regulate blood glucose homeostasis but also improve organ dysfunction, regulate immunity, and control inflammation and other functions in patients with sepsis." (PMID 34335269, 2021). "However, we evaluated sepsis at 3, 6, 12, 24, and 72 h, and compared the changes in GLP-1R expression between CKD and CKD-with-sepsis groups (and where the results were consistent among the timepoints)." (PMID 31795376, 2019). "GLP-1R expression was decreased at 8 weeks after CKD and was lowest in the CKD-with-sepsis group." (PMID 31795376, 2019). "However, the decrease in renal GLP-1R activity at 3 days might not be directly associated with tubular injury because the CKD group, which had a higher serum creatinine level, exhibited higher renal GLP-1R expression than the sepsis-only group." (PMID 31795376, 2019).
cardiac hypertrophy (16 papers, 2010 to 2025). "In hypertensive mice induced by angiotensin II, GLP-1R activation normalized blood pressure and reduced cardiac hypertrophy, vascular fibrosis, endothelial dysfunction, oxidative stress, and vascular inflammation." (PMID 38673991, 2024). "Previous studies have demonstrated that GLP-1R agonist inhibits NOX4-mediated ROS production in high-glucose cultured endothelial cells or angiotensin II-induced cardiac hypertrophy." (PMID 37278349, 2023). "Evidence has recently revealed that GLP-1RAs inhibit cardiac hypertrophy by upregulating GLP-1R expression and activating the AMPK/mechanistic target of the rapamycin (mTOR) signaling pathway." (PMID 34131405, 2021). "Our previous study found that geniposide, an agonist of glucagon-like peptide-1 receptor (GLP-1R), protected against cardiac hypertrophy via the activation of AMP-activated protein kinase α (AMPKα)." (PMID 30533173, 2018). "The present study aims to investigate whether semaglutide, a long-acting GLP1R agonist, can ameliorate cardiac hypertrophy induced by pressure overload, and explore the potential mechanism." (PMID 38782946, 2024). "The GLP1R agonist decreased cardiac hypertrophy and cardiomyocyte hypertrophy." (PMID 38732142, 2024). "Therefore, we focused on the effect of semaglutide, a long-acting GLP1R agonist, on cardiac hypertrophy induced by pressure overload in this study." (PMID 38782946, 2024). "We previously found that geniposide attenuated cardiac hypertrophy via GLP-1R." (PMID 30533173, 2018). "Liraglutide reduced cardiac hypertrophy, decreased cardiomyocyte hypertrophy, and augmented the plasma GLP-1 level and GLP1R expression in myocardial tissue." (PMID 38732142, 2024). "Besides, knockdown of GLP-1R impeded the inhibitory effects of geniposide on cardiac hypertrophy in vivo, suggesting that it protects against cardiac hypertrophy via GLP-1R and AMPKα and indicating that it may be a potential therapeutic candidate for cardiac hypertrophy." (PMID 31118959, 2019). "As an agonist of GLP-1R, geniposide could protect cardiac hypertrophy by activating the GLP-1 receptor/AMPKα pathway, thereby being a potential candidate drug for treating cardiac hypertrophy." (PMID 35630796, 2022).
kidney failure (16 papers, 2021 to 2025). An acute or chronic condition that is characterized by the inability of the kidneys to adequately filter the blood. "In contrast, both sodium glucose cotransporter 2 (SGLT2) inhibitors and glucagon-like-peptide-1 receptor (GLP-1-R) agonists reduce the risk of all-cause mortality, cardiovascular mortality, and kidney failure." (PMID 37623335, 2023).
renal fibrosis (16 papers, 2016 to 2026). A final common manifestation of a wide variety of chronic kidney diseases characterized by glomerulosclerosis and tubulointerstitial fibrosis. "The results showed that the amelioration of renal fibrosis caused by the miR-192 inhibitor was abolished by si-GLP1R." (PMID 29717107, 2018). "Amelioration of the renal fibrosis caused by the miR-192 inhibitor was abolished by si-GLP1R." (PMID 29717107, 2018). "In summary, this study demonstrates that TB001, a novel GCGR/GLP-1R co-agonist, can effectively alleviate renal fibrosis in pre-clinical models, likely by attenuating PERK-mediated ER stress and EMT in tubular cells." (PMID 41280890, 2025). "This study demonstrated that TB001, a novel GCGR/GLP-1R co-agonist, effectively attenuates renal fibrosis in pre-clinical models, potentially through the inhibition of PERK-mediated ER stress in tubular cells." (PMID 41280890, 2025). "Icariin can alleviate DKD renal fibrosis by restoring autophagy through the miR-192-5p/GLP-1R pathway." (PMID 36234757, 2022). "Using TargetScan and gain- and loss-of-function experiments, the authors confirmed that miR-192 promoted renal fibrosis by targeting glucagon-like peptide 1 receptor (GLP1R)." (PMID 33918699, 2021). "In an experimental model of renal fibrosis, GLP-1R activation prevents epithelial-mesenchymal transition and ECM deposition by inhibition of TGF-β1/Smad3 and ERK1/2 signalling pathways." (PMID 33093510, 2020). "To verify that miR-192 promotes renal fibrosis through GLP1R, we co-transfected HK-2 cells with both si-GLP1R and a miR-192 inhibitor." (PMID 29717107, 2018). "Similar to this study, our data showed that the novel GCGR/GLP-1R dual agonists TB001 could ameliorate renal fibrosis by downregulating tubular cell EMT." (PMID 41280890, 2025). "In this study, we aimed to investigate whether TB001, a novel dual GCGR/GLP-1R agonist, ameliorates renal fibrosis by inhibiting the PERK-mediated endoplasmic reticulum stress pathway, using well-established in vivo and in vitro models." (PMID 41280890, 2025). "However, studies on the effects of GCGR or GLP-1R agonists on renal fibrosis and ER are still limited." (PMID 41280890, 2025). "Our in silico analyses of public data show a reduction in GLP-1R expression in the kidney samples from mice submitted to UUO (logFC = −3,27 [GSE87212] and logFC = −1,02 [GSE38117]), supporting the use of a GLP-1R agonist as an interesting therapeutic alternative in remodeling of renal fibrosis." (PMID 37927592, 2023). "Similarly, in other models of cardiac and renal fibrosis, the activation of GLP-1R was able to reduce the fibrotic process." (PMID 33093510, 2020). "In addition, blocking GLP-1R signalling with Ex-3 reduced the protective role of SG in renal fibrosis." (PMID 29607314, 2018). "To evaluate the role of GLP1R in renal fibrosis, we transfected HK-2 cells with si-GLP1R." (PMID 29717107, 2018). "To explore whether miR-192 promotes renal fibrosis through GLP1R, we co-transfected HK-2 cells with both si-GLP1R and a miR-192 inhibitor." (PMID 29717107, 2018). "Finally, we demonstrated that the amelioration of renal fibrosis by exendin-4 occurred through a miR-192-GLP1R pathway, indicating a new pathway by which exendin-4 regulates GLP1R." (PMID 29717107, 2018). "Whether dual GCGR/GLP-1R agonists confer protection against renal fibrosis remains unclear." (PMID 41280890, 2025).
renal fibrosis (continued). "Moreover, we evaluated the role of GLP1R in renal fibrosis and observed that si-GLP1R significantly upregulated FN and Col-I at both the mRNA and protein levels, which indicated that GLP1R has a role in renal fibrosis." (PMID 29717107, 2018). "The mouse model of unilateral ureter obstruction (UUO) was used to determine the efficacy of the dual GCGR/GLP-1R agonist, TB001 in the protection of renal fibrosis." (PMID 41280890, 2025). "In this study, we aimed to determine the efficacy of a novel GLP-1R and GCGR co-agonist, TB001 in the development of renal fibrosis using both in vitro and in vivo models." (PMID 41280890, 2025). "In the present study, we demonstrated that the oligo-fucoidan greatly improves renal fibrosis under diabetic condition through inhibition of TGF-β1-activated pro-fibrogenic pathway via activation of Sirt-1, GLP-1R, and Nrf2/HO-1." (PMID 33049944, 2020). "In this study, our results demonstrated that dual GLP-1R and GCGR agonist TB001 could significantly ameliorate renal fibrosis in UUO mouse models and in vitro cell culture systems." (PMID 41280890, 2025). "Even though both fractions could improve renal function and alleviate renal fibrosis, only F2 was able to reverse the DPP-4 and GLP-1R levels as well as attenuate oxidative stress in the kidney." (PMID 39856844, 2025). "In renal fibrosis, ICA can restore autophagy by modulating the miR-192-5p/GLP-1R pathway." (PMID 40535758, 2025). "Moreover, miR-192 targets GLP-1R by binding to its 3′-UTR and promotes renal fibrosis through reducing GLP-1R expression." (PMID 34349660, 2021). "For example, quercetin, a dietary flavonoid, can reduce RTEC senescence in renal fibrosis via SIRT1/PINK1/mitophagy axis, while liraglutide, a glucagon-like peptide-1 receptor agonist, can improve mitochondrial homeostasis in heart injury through the identical signaling axis." (PMID 34359852, 2021). "However, in this study, we did not examine the mechanism by which GLP1R regulates renal fibrosis." (PMID 29717107, 2018). "In addition, other than the kidney cells, various other cell types in liver, pancreas, and blood vessels also expressed GLP-1R and GCGR; it cannot be ruled out that TB001 exerts its effect through these organs or cell types and indirectly prevents renal fibrosis." (PMID 41280890, 2025).
endometrial cancer (14 papers, 2018 to 2026). Primary or metastatic malignant neoplasm involving the endometrium (mucous membrane that lines the endometrial cavity). "Here, we investigated the effects of the GLP-1R agonist liraglutide in endometrial cancer cells and examined the association between GLP-1R expression and clinicopathological characteristics in endometrial cancer patients." (PMID 29907137, 2018). "They further showed that all endometrial cancer tissues expressed GLP-1R, but the mechanism of GLP-1R-induced apoptosis and the association between clinicopathological characteristics of endometrial cancer patients and GLP-1R expression remains to be elucidated." (PMID 29907137, 2018). "Furthermore, higher GLP-1R expression may be associated with better prognosis in endometrial cancer patients." (PMID 29907137, 2018). "GLP-1R transcription is significantly induced upon treatment of Ishikawa endometrial cancer cells with GLP-1R agonists liraglutide or semaglutide beginning at 24 h, with continued induction through 48 h." (PMID 40002193, 2025). "Glucagon-like peptide-1 receptor (GLP1R), a seven-transmembrane protein encoded by the GLP1R gene, is upregulated in endometrial cancer (EC) and promotes proliferation and metastasis, thereby accelerating EC progression." (PMID 40696350, 2025). "The induction of GLP-1R in response to agonist binding predicts a feed-forward loop of activity for agents such as liraglutide and semaglutide in endometrial cancer cells." (PMID 40002193, 2025). "Since our goal is to assess the combination of a GLP-1R agonist with a progestin, in subsequent experiments, we focused on Ishikawa cells, which are endometrial cancer cells with PR expression." (PMID 40002193, 2025). "The findings showed that liraglutide, an activator of GLP-1R, increased the levels of GLP-1R in Ishikawa endometrial cancer cells and inhibited the growth of these cells depending on the dosage." (PMID 39429275, 2024). "Tissue samples were used by them to examine the pathological functions of GLP-1R in individuals with endometrial cancer." (PMID 39429275, 2024). "The significant rise in cAMP levels in endometrial cancer cells was a result of the heightened expression of GLP1R." (PMID 39429275, 2024). "The search was carried out on Medline using the keywords glucagon-like-peptide-1 receptor agonists, endometrial cancer, and conservative treatment, in combination with the boolean operators AND or OR." (PMID 39429275, 2024). "An additional potential role of studying GLP-1R is to understand how it affects how human endometrial cancer cells respond to chemotherapy when in high glucose conditions." (PMID 39429275, 2024). "In another study, Kanda and colleagues demonstrated that glucagon-like peptide-1 receptor (GLP-1R) agonist liraglutide stimulates autophagy via AMPK pathway in endometrial cancer cells." (PMID 31850214, 2019). "Authors first showed that treatments with GLP-1R agonist significantly inhibited Ishikawa endometrial cancer cells growth and induced apoptosis." (PMID 31850214, 2019). "GLP-1R expression was evaluated in endometrial cancer tissue samples from 154 patients based on the Allred score." (PMID 29907137, 2018). "Our results thus clearly demonstrated the mechanism of a GLP-1R agonist in endometrial cancer cells." (PMID 29907137, 2018). "First, our results showed that GLP-1R expression was elevated by liraglutide in a dose-dependent manner in Ishikawa endometrial cancer cells." (PMID 29907137, 2018). "Here, we investigated the physiological effect of liraglutide, a GLP-1R agonist, in Ishikawa endometrial cancer cells, and the pathological roles of GLP-1R in patients with endometrial cancer were analyzed using tissue samples." (PMID 29907137, 2018). "Endometrial cancer tissues also expressed GLP-1R, and high GLP-1R expression was clearly associated with better PFS." (PMID 29907137, 2018).
endometrial cancer (continued). "A previous report showed that a glucagon-like peptide-1 receptor (GLP-1R) agonist (exenatide) induced apoptosis in endometrial cancer cells." (PMID 29907137, 2018). "Sex-specific factors are equally important, particularly in hormone-sensitive cancers such as breast and endometrial cancers, which may exhibit unique responses to GLP-1R signaling." (PMID 39777709, 2025). "In general, GLP-1R agonists may attenuate endometrial cancer growth and tumor progression, potentially through increasing the sensitivity of cells to progesterone, which is a standard antiproliferative treatment for endometrial hyperplasia." (PMID 41178720, 2025). "GLP-1R agonists could stimulate autophagy and induce apoptosis of endometrial cancer cells via the AMPK pathway." (PMID 35321716, 2022). "In this study, we shed light on the pathophysiological role of GLP-1R in endometrial cancer." (PMID 29907137, 2018). "Moreover, a previous report suggested that exenatide, a GLP-1R agonist, induced apoptosis in endometrial cancer cells." (PMID 29907137, 2018). "Liraglutide induced apoptosis and autophagy via the AMPK signaling pathway, and GLP-1R may be a biomarker of endometrial cancer, as higher GLP-1R expression was be associated with better prognosis in endometrial cancer patients." (PMID 29907137, 2018). "GLP-1R was predominantly localized in the cytoplasm in endometrial cancer tissue." (PMID 29907137, 2018). "Moreover, using a tissue microarray, we analyzed GLP-1R expression in 154 endometrial cancer tissue samples by immunohistochemistry." (PMID 29907137, 2018). "We first investigated whether endometrial cancer cells express GLP-1R by Western blot analysis." (PMID 29907137, 2018). "GLP-1R was also found in human endometrial cancer cells, indicating that GLP-1R is highly expressed in both cancerous and non-cancerous endometrial cells." (PMID 39429275, 2024). "However, the pathophysiological role of GLP-1R in endometrial cancer has not been fully elucidated." (PMID 29907137, 2018).